TNF (tumor necrosis factor)
Diseases named in the same sentence as TNF in open-access papers (continued):
Sharing a sentence is not in itself a finding about the gene and the disease.
COVID-19 (continued). "In COVID-19, there was a strong positive correlation between Gal-3 and interleukin-1 beta (IL-1β), as well as a moderate positive correlation between Gal-3, TNF-α, and IL-12, indicating a T-helper 1 (Th1) immune response." (PMID 37298569, 2023). "The COVID-19 induced IL-17 immune response and TNF-α release can worsen psoriasis and its comorbidities." (PMID 38029150, 2023). "TNF-α levels returned to normal values as early as 2.5 months after hospital admission in post-COVID-19 female patients." (PMID 37896963, 2023). "Severe pulmonary disease symptoms of COVID-19, which are a consequence of tissue damage due to an exacerbated inflammatory response, are marked by elevated levels of TNF-α, IL-1β, and other inflammatory mediators." (PMID 37854602, 2023). "COVID-19 patients treated with Tranilast had apparently lower levels of proinflammatory cytokines (e.g., IL-1β, IL-6 and TNF-α) than the controls." (PMID 37251383, 2023). "Recent studies show that an abnormal diffuse inflammatory cytokine profile can persist in long COVID-19 subjects for at least 8 months, along with the persistent deregulation of IL-1β, IL-6, and TNF-α." (PMID 37887357, 2023). "We found that monocytes from convalescent COVID-19 patients expressed significantly lower levels of both TNF-α and IL-6 in response to LPS stimulation, consistent with our findings regarding the expression of activation markers and cellular CD142." (PMID 38250080, 2023). "An underlying characteristic in the pathophysiology of airway diseases such as asthma, COVID-19, or chronic bronchitis is inflammation mediated by pro-inflammatory cytokines, such as tumor necrosis factor alpha (TNFα)." (PMID 37958799, 2023). "Amongst those with acute COVID-19, eleven markers significantly differed across disease severity categories: IL-1β, IL-2, IL-6, IL-10, IL-18, IL-23, IL-33, TNF-α, IP-10, G-CSF and YKL-40." (PMID 37063871, 2023). "Other studies, however, have demonstrated that the levels of IL-6, IFN-, and TNF in pediatric COVID-19 were stable and unchanged." (PMID 36839601, 2023). "Clinical studies have shown abnormal concentrations of different relevant cytokines in patients with COVID-19, such as IL-6, TNF-α, IL-1β." (PMID 38018195, 2023). "Patients with inflammatory bowel diseases (IBDs) treated with antitumor necrosis factor (TNF)-α have lower serologic response after two COVID-19 vaccine doses." (PMID 37515078, 2023). "One of the most commonly targeted cytokines in rheumatology was TNF alpha, and as the use of TNF inhibition in patients with SARD was associated with less frequent COVID-19 infection, it was natural for this to be a potential treatment for COVID-19." (PMID 36987476, 2023). "Another study analyzing SARS-CoV-2-specific T cells in asymptomatic and symptomatic COVID-19 patients, showed that the levels of IFNγ, interleukins-2, 6, and TNF were higher in the asymptomatic cases than in the symptomatic patients." (PMID 37869674, 2023). "Recently, Anti-tumor Necrosis Factor (TNF) therapy has been debated for its potential protective action in severe COVID-19 treatment as shown in a study by Neurath9." (PMID 37081046, 2023). "Because IFN-γ potentiates the effects of LPS, we stimulated the IFN-γR with IFN-γ plus LPS and measured the TNF-α secretion in COVID-19 patients and healthy controls." (PMID 37189696, 2023). "TNFα levels significantly correlated with the severity of acute COVID-19 illness (spearman’s r = 0.30, p < 0.05)." (PMID 36844209, 2023). "According to previous studies, after adult infection with COVID-19, TNF-α, interleukin and other indicators have significant changes, and even some severely infected individuals have excessive inflammation and cytokine storm phenomena." (PMID 37565246, 2023). "Elevated serum levels of TNF-α and soluble TNF-Receptor 1 have been detected in COVID-19 patients with severe infection, providing a rationale for the use of TNF-α inhibitors in SARS-CoV-2 infection." (PMID 38203525, 2023).
COVID-19 (continued). "The hsa-miR-146a-5p increase we observed in post-COVID-19 patients is an indication of the path to recovery, as the levels of IL-1, IL-6 and TNF-α cytokines are inversely correlated to has-miR-146a production." (PMID 38110483, 2023). "Our work also observed a significant increase in the tissue expression of TNF-α and NF-kB in the COVID-19 group compared to the CONTROL group." (PMID 36992415, 2023). "The administration of a probiotic mix to 19 patients discharged after hospitalization for COVID-19 indicated that serum citrulline levels, IL-6, IL-12RA, and TNF-α were significantly reduced at the end of treatment (week 8) compared to baseline levels." (PMID 37763251, 2023). "It has been suggested that T cells from COVID-19 patients undergo apoptosis due to the macrophage-derived TNF-α." (PMID 37654571, 2023). "The role of TNF-α in worsening the clinical picture of COVID-19, ARDS, and systemic inflammation, is well known." (PMID 36851291, 2023). "Increased cytokine levels (IL-6, IL-10, and TNF-α) and decreased IFN-γ expression in CD4+ T cells have been associated with severe COVID-19 in adults." (PMID 37602239, 2023). "Our results showed significantly higher level of IL-1β, TNF-α, IL-12 and IL-10 in patients with stage IV of COVID-19 in comparison to milder forms of the disease." (PMID 36702907, 2023). "A study examined the immunological responses of 13 COVID-19 patients and observed that the illness has elevated cytokines proportion with IL-6, IL-10, and TNF-alpha, along with enhanced monocytes and neutrophil counts." (PMID 37754237, 2023). "Though seemingly contradictory to immune evasion mechanisms, enhanced innate immune activation, including systemic type I IFN, IL-1β, IL-6, and TNF-α production, contributes to morbidity and mortality in COVID-19." (PMID 37892134, 2023). "Overall, higher IL-1β, IL-6, and TNF- α levels were reported in COVID-19-infected patients compared to patients with periodontitis." (PMID 37106750, 2023). "An observed high serum level of TNF-α in COVID-19 patients has indicated a potential role of targeting TNF-α." (PMID 36839968, 2023). "Miyashita and colleagues investigated the correlation between pro-inflammatory cytokine levels in sera and AEs after the COVID-19 vaccination, and they found that systemic TNF-α levels were connected with the systemic scores after the second dose." (PMID 37112659, 2023). "Anti-TNF-α therapies as well as destiffening therapies have been suggested to combat severe COVID-19." (PMID 36674700, 2023). "Upstream regulator analysis showed strong activation scores for many cytokines, including IFNs, TNF, and IL-1β, in the T/NK cells of patients with COVID-19." (PMID 37606044, 2023). "The hyper-inflammatory response observed in COVID-19, manifesting as a cytokine storm, contributes to disease severity by increasing serum levels of IL-6, IL-8, TNF-α, and IL-1β." (PMID 37372128, 2023). "Studies have reported an increase in the plasma levels of IL-6 and TNF-alpha in hospitalized COVID-19 patients." (PMID 37951972, 2023). "Anti-TNF medication produced a significantly impaired humoral immune response to vaccination against COVID-19." (PMID 37560623, 2023). "TNF inhibitors significantly reduce the humoral response following dual vaccination against COVID-19 in patients with RA." (PMID 37560623, 2023). "As a result, it further implies the importance and feasibility of employing TNF-α in the prognosis of severe COVID-19." (PMID 37047115, 2023). "The COVID-19 infection instils a cytokine storm releasing pro-inflammatory cytokines like IL-6, IL-1, TNF- α and interferon which explains the abundant load of inflammatory cells in COVID-19 positive cases." (PMID 36806020, 2023). "COVID-19 progression involves pulmonary hyper-inflammation and release of pro-inflammatory cytokines (e.g., TNF-α, IL-6, IL-1, IL-8, and MCP-1), as part of “cytokine storms”." (PMID 36825200, 2023).
COVID-19 (continued). "Although TNF-α is not as relevant as interleukin-6 on the cytokine storm presented in severe COVID-19 patients, anti-TNF-α drug repositioning for COVID-19 has been proposed." (PMID 35432458, 2022). "This is explained in our study by the significant positive correlation of TNF-α with IL-6 and age in COVID-19 patients." (PMID 36381078, 2022). "It was shown that levels of serum interleukins and TNF-a in hospitalized COVID-19 patients were strong and independent predictors of disease severity and death." (PMID 36140256, 2022). "• IL-6 plays a main role in COVID-19 severity, while TNF-α and IL-1β trigger the NF-κB signaling pathway." (PMID 35422702, 2022). "In COVID-19 patients, high levels of TNF-α, IL-1β, IL-4, IL-6, IL-10, IP-10, MCP-1, and MIP-1A have been detected, and particularly, high IL-6 concentrations are positively correlated with the severity of the disease." (PMID 35744777, 2022). "The studies indicate that the levels of IL-2, IL-6, IL-7, IL-10, and TNF-α are elevated in COVID-19; moreover, the increased IL-6 levels were found to be associated with disease progression and severe cases." (PMID 35656183, 2022). "In a study comparing the anti-inflammatory function of HDL in COVID-19 patients with healthy controls, the authors demonstrated less protection for endothelial cells stimulated with TNFα." (PMID 36290581, 2022). "We found that COVID-19 vaccination enhanced the mobilization of SARS-CoV-2-reactive TNFα-producing CD4+ and CD8+ T cells, and this enhancement was significant after the second dose of the vaccine was administered." (PMID 35669765, 2022). "The effect of TNF antagonists on serological responses of COVID-19 vaccination is becoming well documented in the literature." (PMID 35860742, 2022). "Patients with COVID-19 have positively correlated with systemic elevation of pro-inflammatory cytokines IL-6 and TNF-α." (PMID 35783877, 2022). "Serum levels of inflammatory cytokines including IL-6, G-CSF, IP-10, MCP1, MIP1A, and TNF are elevated in COVID-19 patients within intensive care units (ICU), which indicates the occurrence of cytokine storm in these patients." (PMID 36458163, 2022). "The rise of concentrations of TNFα, witnessed within our study, is a common finding in COVID-19 patients; this pro-inflammatory cytokine is often designated with the role of severity predictor." (PMID 36430621, 2022). "In agreement with previous studies, our analyses of cytokine profiles revealed different dynamics of IL-2R, IL-6, IL-8, IL-10, and TNF-α during the disease progression of COVID-19." (PMID 35248063, 2022). "One of the most striking clinical features of COVID-19 patients is the dysregulated immune response, which leads to a cytokine storm, that is, the overproduction of proinflammatory cytokines (TNF-α, IL-1, and IL-6) and chemokines (IL-8)." (PMID 36211421, 2022). "As regards the cytokines panel, all but IFNγ and TNFα showed increased serum concentration in COVID-19 patients with more severe pneumonia." (PMID 35563218, 2022). "Our analysis show that the mean levels of IL-6 and TNF-α were significantly different in the study groups, with higher levels in COVID-19 patients and those residing at high altitude." (PMID 35090394, 2022). "COVID-19 is characterized by unique hyperinflammatory signatures across all types of immune cells, particularly the upregulation of TNF-α-, IL-6-, and IL-1-driven inflammatory responses in severe disease." (PMID 35464491, 2022). "These targeted therapies are used to treat both inflammatory diseases with more aggressive phenotypes, and severely ill patients with COVID-19, considering the major contribution of TNF and IL-6 to the cytokine-storm syndrome observed in critical patients." (PMID 35770002, 2022). "Increased circulating levels of the pro-inflammatory cytokines IL-1β, IL-6, IL-8, and TNF-α are hallmarks in the immunopathology of chronic inflammatory diseases, including COVID-19." (PMID 35563697, 2022).
COVID-19 (continued). "Below, we review the possibilities and challenges of targeting the TNF-α pathway in COVID-19 treatment." (PMID 35223745, 2022). "Further, impaired T cell function, increased release of inflammatory mediators, especially TNFα and IL-1β, and elevated levels of ACE2 also played a crucial role in developing severe COVID-19 symptoms and predisposed to higher mortality risk." (PMID 36589459, 2022). "Highlighting the functional impairments, NK cells from people with COVID-19 co-cultured with virally-infected cells were less able to produce IFNγ and TNFα and reduce virus protein levels than th ose isolated from healthy individuals." (PMID 38566903, 2022). "Elevated pro-inflammatory cytokine is a typical profile in patients with COVID-19, such as IL-6, IL-1, and tumor necrosis factor (TNF)-α." (PMID 35957855, 2022). "The tear film concentrations of VEGF and IL-10 were found to be significantly increased, whereas TNF-α, IL-1β, IL-8, and GM-CSF were significantly lower among the COVID-19 patients admitted to the hospital than among the SARS-CoV-2-negative controls." (PMID 35566776, 2022). "KLF2 plays a significant role in COVID-19 as SARS-CoV-2 significantly down-regulates KLF2 expression: COVID-19 patients have elevated serum levels of TNF-α and IL-1 and decreased KLF2 gene expression." (PMID 35409070, 2022). "It is explained theoretically that the “new use of old drugs” of TNF and IL-17 inhibitors increases the possibility of treating COVID-19 as a new indication." (PMID 35935817, 2022). "Patients with severe COVID-19 also reported higher serum levels of pro-inflammatory cytokines (TNF-α, IL-1 and IL-6) and chemokines (IL-8), suggesting a possible role for hyper-inflammatory responses in the pathogenesis of COVID-19 disease." (PMID 35453526, 2022). "A not yet published study showed a long-lasting cytokine signature in patients with prior COVID-19 where IL-1β, IL-6, and TNF-α showed a significant correlation with post-acute COVID-19." (PMID 35883640, 2022). "The mean levels of TNF-α were higher in COVID-19 patients, in the age group 51-80 years old than the age group 20-50 years, whereas IL-6, testosterone, and inhibin B levels were not significantly different between 20-50 years and 51-80 years subgroups." (PMID 36381078, 2022). "COVID-19 patients show higher concentrations of IL-2, IL-7, IL-10, G-CSF, IP10 (CXCL10), MCP-1 (CCL2), MIP1a (CCL3) and TNF-α than non-COVID-19 patients." (PMID 35901034, 2022). "On another note, levels of TNF-α and IL-17A were similarly more elevated in the mild-moderate and severe COVID-19 patients than in healthy controls." (PMID 35529862, 2022). "Of note, inflammatory cytokine milieu characterized in chronic HIV infection shares overlapping targets that are also identified in severe COVID-19, featuring increased level of interleukin-6 (IL-6), IL-10 and tumor necrosis factor (TNF)." (PMID 34843064, 2022). "This was investigated further using CRP, TNF-α, IL-6, and procalcitonin measurements from plasma samples from hospitalized people with COVID-19 in the ISARIC4C study." (PMID 35531376, 2022). "In pregnancy, IFNs and cytokines play important roles in the immune responses promoting healthy pregnancy as well as congenital disorders and complications, similar to those activated during a COVID-19 cytokine storm, including TNF-α." (PMID 35319475, 2022). "This cytokine storm causes an increase in T-helper (Th)-1 cytokines, including TNF-α, IL-1β, CCL2, CXCL10, IL-6, and IFN-γ, and Th-2 cytokines, including IL-10, IL-4, and IL-1 receptor antagonists in the serum of COVID-19 patients." (PMID 35053059, 2022). "Tumor necrosis factor alpha (TNF-α) is another important inflammatory cytokine that shows increased production in patient with moderate to severe COVID-19." (PMID 36182930, 2022).
COVID-19 (continued). "This study investigated the correlation between proinflammatory cytokine levels in sera and adverse reactions after COVID-19 vaccination, and found that systemic TNF-α levels were connected with the systemic scores after the second dose." (PMID 35136071, 2022). "COVID-19 patients exhibit unique coagulopathy, characterized by thrombus formation with elevated levels of cytokines, including tumor necrosis factor (TNF)-α, interleukin (IL)-8, and IL-6, among others." (PMID 36466841, 2022). "Based on the COVID-19 cytokine literature, we identified 6 cytokines (IL-1β, IL-2, IL-6, IL-8, IL-10, and TNF-α) commonly found in critically ill COVID-19 patients." (PMID 35033181, 2022). "Regarding the relationship between TNFα and COVID-19, TNFα is involved in acute inflammatory reactions and acts as an inflammation amplifier." (PMID 36417106, 2022). "A team studied the immune responses of 54 COVID-19 patients and found that TNF-α and IL-6 production by circulating monocytes was sustained." (PMID 35223745, 2022). "A few studies have reported recovery in a patient with COVID-19 treated with TNF-α inhibitor etanercept successfully." (PMID 35223745, 2022). "On the other hand, the TNF-alpha signaling pathway was enriched in COVID-19 relative to other-viral ARIs." (PMID 35922752, 2022). "The proportion of participants with elevated TNF-α in survivors of COVID-19 was significantly higher than that of healthy controls (p < 0.01) and higher than that of risk factor-matched controls (p < 0.01)." (PMID 35237624, 2022). "When not inhibited by TIMP-3, due to low SIRT1 activity-mediated TIMP-3 reduction, ADAM17 causes the release of TNF-α and IL6 and contributes to inflammation and possibly to the development of an uncontrolled hyperinflammatory response in COVID-19." (PMID 35457123, 2022). "The most relevant results are that resistin, IL-6, IL-8, IL-15, IL-18, MCP-1 and TNF-α are the main cytokines associated to COVID-19 symptomatology; meanwhile resistin, IL-8, IL-15, MCP-1 and TNF-α used to be associated with oxygen therapy necessity." (PMID 35330391, 2022). "We identified SARS-CoV-2 dsRNA sequences in COVID-19 plasma exosomes, which stimulated the production of IL-6, IL-8, TNF-α and other cytokines by PBMC from healthy donors." (PMID 36526691, 2022). "Despite the suppression of host IFN signaling by SARS-CoV-2 infection, levels of cytokines/chemokines, such as IL-6, IL-8, IP-10, and TNF-α, are significantly elevated in COVID-19 patients." (PMID 35856559, 2022). "An elevated level of several other pro-inflammatory cytokines, including tumor necrosis factor-α (TNFα), IL-8, IL-1β, IL-10, IL-2, IL-4, soluble IL-2 receptor (sIL-2R), and interferon-γ (IFNγ) were also observed in severe COVID-19 patients." (PMID 35677336, 2022). "The majority of SARS-CoV-2–specific CD4+ T cells produced at least 2 cytokines, and IL-2+TNF-α+ SARS-CoV-2–specific CD4+ T cells were the dominant subpopulation of the COVID-19 immune landscape." (PMID 35230977, 2022). "Now, in the current study, we found that the enhanced plasma concentration of IL-26 displays a strong correlation with that of IL-8, and a somewhat weaker one with that of TNFα, in the COVID-19 group." (PMID 36466824, 2022). "A quarter of the patients with progression to COVID-19-associated ARDS presented with macrophage activation syndrome: high levels of CRP, ferritin, d-dimer, AST/ALT, tumor necrosis factor (TNF)-alpha, interleukin (IL)-1beta and IL-6." (PMID 36289881, 2022). "Evidence supporting the importance of targeting TNF-α in COVID-19 positive patients comes from observational data on humans extrapolated from three large registries." (PMID 36579506, 2022). "The integrated areas of the regions related to IFN-γ, TNF-α, IL-1 β, IL-6, and IL-10 were obtained to elucidate the quantity of those cytokines in the V-COVID-19 and V-Healthy groups." (PMID 36497139, 2022).